PRMT3 (protein arginine methyltransferase 3)
Diseases named in the same sentence as PRMT3 in open-access papers (continued):
Sharing a sentence is not in itself a finding about the gene and the disease.
tumor (continued). "In inflammatory conditions, cGAS/STING pathway activation can be beneficial for eliminating tumor cells, and PRMT3’s suppression of this pathway may represent a protective mechanism that cancer cells exploit." (PMID 41583428, 2025). "By analyzing PRMT3 expression in HCC patients who received immunotherapy, we found that PRMT3 was notably higher in tumor samples from patients who received anti-PD-1/PD-L1 therapy at both mRNA and protein levels than in tumor samples from patients who did not." (PMID 39256398, 2024). "Interestingly, PRMT3-OE led to a small but significant increase in the tumor volumes and weights and a decrease in T cell infiltration (CD4+, CD8+, and IFNγ+ and GZMB+ CD8+ T cells) in HSP60-R446K OE cells compared to vector control." (PMID 39256398, 2024). "Collectively, our findings suggest that HSP60 may be a key substrate of PRMT3 that plays an important role in PRMT3-mediated suppression of anti-tumor immunity." (PMID 39256398, 2024). "Also, co-expression of PRMT3 with HSP60-R446K mutant had a less profound effect on tumor progression and immune infiltration inhibition than co-expression of PRMT3 with HSP60-R446K." (PMID 39256398, 2024). "To determine whether PRMT3 also plays a role in suppressing anti-tumor immunity in other cancer types, we analyzed the correlations between T cell infiltration and PRMT3 mRNA expression levels in various cancer types using Timer 2.037." (PMID 39256398, 2024). "Given the significant changes in T cell abundance by Prmt3-KO and PRMT3 inhibition, we then examined whether the effects of Prmt3-KO and PRMT3 inhibition on tumor progression were mediated by CD8+ or CD4+ T cells." (PMID 39256398, 2024). "PRMT3 is frequently upregulated and has been proven to promote tumor progression in HCC43, but its role in anti-tumor immunity is largely unknown." (PMID 39256398, 2024). "To further examine whether cGAS hyperactivation directly contributes to the delayed tumor progression and increased T cell infiltration observed in Prmt3-KO tumors, we knocked down cGAS in Prmt3-KO Hepa1-6 cells." (PMID 39256398, 2024). "Also, immunofluorescence (IF) and flow cytometry analyses revealed that PRMT3 inhibition led to a robust increase in the abundance of tumor-infiltrating CD4+ and CD8+ T cells, including IFNγ + CD8+ and GZMB+ CD8+ T cells." (PMID 39256398, 2024). "Because high PRMT3 expression inhibited anti-tumor immunity and efficacy of ICB by methylating HSP60, our findings suggested that PRMT3 might be an important regulator of secondary immunotherapy resistance in HCC." (PMID 39256398, 2024). "Thus, the effects of pharmacologic inhibition of PRMT3 on tumor growth is likely to mediate through inhibition of PRMT3 in cancer cells." (PMID 39256398, 2024). "Previous studies had revealed the role of PRMT3 in chemoresistance, tumor growth, and metabolism." (PMID 37024475, 2023). "Thus, we decided to compare the response to OXA using HCC PDCs derived from patients with PRMT3-high or PRMT3-low tumors as determined by IHC presurgical tumor specimen." (PMID 37024475, 2023). "Moreover, knockdown of HEG1 markedly overcame the OXA resistance induced by PRMT3 OE in HepG2 cells in vivo as shown by weekly measurement of tumor volumes and tumor weights at the endpoint." (PMID 37024475, 2023). "Similarly, Western blotting analyses and IHC assays also showed that PRMT3 protein expression was remarkably higher in HCC tissues compared with matched adjacent non‐tumour tissues." (PMID 35090076, 2022). "Our knockdown and gain-of-function experiments indicate that PRMT3 is critical for both tumor cell growth and survival given that PRMT3 may modify a variety of substrates in different signaling pathways." (PMID 36351894, 2022). "PRMT3 has been shown to promote the migration and invasion of tumor cells." (PMID 36351894, 2022).
tumor (continued). "Furthermore, immunostaining staining showed a significant increase in cleaved-caspase 3 expression in orthotopic tumor xenografts with PRMT3-depleted GSC 20 cells." (PMID 36351894, 2022). "Moreover, immunostaining of cleaved-caspase 3 showed a significant increase in apoptotic cells within PRMT3-knockdown tumors, suggesting that PRMT3 knockdown induces tumor cell apoptosis in the subcutaneous model." (PMID 36351894, 2022). "Histology analysis indicated that PRMT3-knockdown tumors exhibited a reduced tumor mass." (PMID 36351894, 2022). "In addition, xenograft tumor assays showed that PRMT3-mediated tumorigenesis was dependent on HIF1α R282 methylation, and cross-talks between PRMT3-mediated tumorigenesis and HIF1 signaling pathways are implicated in tumor angiogenesis." (PMID 34753906, 2021). "Moreover, The findings from IHC assays indicated that upregulation of PRMT3 significantly increased tumor angiogenesis in tumors induced by cells expressing HIF1α WT, but not cells expressing HIF1α R282K." (PMID 34753906, 2021). "The results showed that PRMT3 knockout suppressed tumor growth and increased cell apoptosis." (PMID 31324208, 2019). "We also identified genetic alteration of the arginine methyltransferase, PRMT3, specifically in the MD/PD tumours, further indicating that epigenetic modifiers may regulate cSCC progression." (PMID 30202019, 2018). "Furthermore, PRMT3‐OE notably promoted tumor to chemoradiation therapy." (PMID 41147802, 2025). "Furthermore, PRMT3 plays a relatively complex role in the tumor immune microenvironment, primarily promoting immune suppression by regulating mitochondrial homeostasis and innate immune signaling pathways, thereby helping tumor cells evade attacks from the immune system." (PMID 41154773, 2025). "Since PRMT3 inhibition activated cGAS/STING signaling through promoting mtDNA release, we decided to examine whether cGAS/STING hyperactivation directly contributes to the delayed tumor progression and increased T cell infiltration observed in Prmt3-KO or PRMT3 inhibitor-treated tumors." (PMID 39256398, 2024). "Also, IGF2BP1-R452K mutant significantly diminished the effect of PRMT3-OE on tumor growth." (PMID 37024475, 2023). "Notably, blocking PRMT3 improves tumor suppression in response to cisplatin and radiation therapy." (PMID 37973560, 2023). "Our study reveals that in NSCLC cells, upregulated PRMT3 promotes IDO1 expression by methylating TFAP2A, thereby activating the tumor’s intrinsic Kyn metabolism and mediating the development of radiation resistance." (PMID 41129671, 2026). "In this study, we identified the tumor-intrinsic PRMT, PRMT3, as a significant player in the resistance to radiotherapy of NSCLC, regulating Kyn metabolism via the TFAP2A–IDO1 axis within tumor cells." (PMID 41129671, 2026). "PRMT3 and CARM1(also known as PRMT4), being type I protein arginine methyltransferases, are key in controlling tumour progression by catalysing the mono‐methylation and asymmetric di‐methylation of both histone and non‐histone substrates." (PMID 39964832, 2025). "Despite these findings, the role of PRMT3 in HCC and its impact on tumor immunity through metabolic reprogramming remain underexplored." (PMID 40050608, 2025). "Our study demonstrates that anti-PD-L1 therapy effectively counteracts the tumor-promoting effects of PRMT3 and restores CD8+ T cell infiltration in mouse tumor models." (PMID 40050608, 2025). "In cancer, PRMT3 drives glycolysis by methylating LDHA and HIF1α, promoting tumor growth and immune evasion." (PMID 41583428, 2025). "It suggests that PRMT3 acts as an oncogenic factor in HCC, and targeting PRMT3 with its inhibitor, SGC707, effectively diminishes PRMT3-induced glycolysis and tumor growth, presenting a novel therapeutic approach for HCC treatment." (PMID 39826691, 2025). "The expression of PRMT1, PRMT3, PRMT4, PRMT5, and PRMT7 was elevated in tumor samples compared to normal tissue, while PRMT2, PRMT8, and PRMT9 were decreased." (PMID 40399547, 2025).
tumor (continued). "The interplay between PRMT3 and c-MYC exemplifies the complex regulatory networks in tumor microenvironments, where PRMT3 orchestrates pro-tumorigenic signaling." (PMID 41583428, 2025). "Inhibition of PRMT3 by SGC707 disrupts this methylation process, leading to decreased stability and activity of HIF1α, which in turn attenuates tumor angiogenesis and growth." (PMID 39826691, 2025). "The development of these inhibitors is grounded in a thorough understanding of PRMT3 and CARM1's mechanisms of action within tumours and an extensive analysis of their expression and functionality across different cancer types." (PMID 39964832, 2025). "On the other hand, PRMT3-mediated inhibition of HSP60 methylation activates the cGAS/STING pathway, which enhances the anti-tumor immune response." (PMID 41583428, 2025). "The data revealed a positive correlation between PRMT3 expression and both p-PDHA and PD-L1 levels in tumor tissues." (PMID 40050608, 2025). "Furthermore, our data showed the comparable effects of global (pharmacologic) and genetic inhibition of PRMT3 on tumor growth and therapeutic outcomes, suggesting that PRMT3 inhibitors may mediate its anti-tumor effects through inhibition of PRMT3 expression in cancer cells." (PMID 39256398, 2024). "Overexpression of PRMT3 promotes tumor growth in GBM while also conflicting poor survival with heightened expression; PRMT3 promotes tumorigenesis in GBM by regulating glycolysis, specifically, HIF1A." (PMID 38183103, 2024). "We found that PRMT3 protein and mRNA expression levels were higher in HCC tumor tissues than in the adjacent normal tissues." (PMID 39256398, 2024). "Work in patient-derived GSCs and a nude mouse flank model demonstrated decreased glycolysis, cell growth, and tumor growth with SGC707, a small molecule PRMT3 inhibitor." (PMID 37205197, 2023). "We found that PRMT3 KO dramatically sensitized PLC-8024 cells to OXA treatment, as shown by reduced tumor sizes and weights." (PMID 37024475, 2023). "Decreased expression of Ki67 and increased cleaved caspase 3 were observed in the tumor tissues from the PRMT3-KO cells treated with OXA and tumors from PRMT3-WT cells treated with SGC707 + OXA compared to their corresponding control." (PMID 37024475, 2023). "Overexpression of PRMT3 enhanced the glycolysis in HCC cells, thus promoting cell proliferation and tumour growth." (PMID 35090076, 2022). "Pharmacological inhibition of PRMT3 with a PRMT3 inhibitor SGC707 abolished GBM glycolysis and tumor growth." (PMID 36351894, 2022). "The administration of PRMT3 inhibitor, SGC707, effectively attenuated PRMT3‐induced HCC glycolysis and tumour growth." (PMID 35090076, 2022). "PRMT3 knockdown led to the decrease in proliferation, glycolysis of HCC cells and tumour growth, whilst its overexpression showed opposite results." (PMID 35090076, 2022). "We, then, analysed PRMT3 mRNA expression in 40 pairs of HCC and matched adjacent non‐tumour tissues using quantitative real‐time‐polymerase chain reaction (qRT‐PCR)." (PMID 35090076, 2022). "Motivated by these results, we also presented data regarding the effectiveness of the PRMT3 inhibitor, SGC707, in suppressing PRMT3‐induced HCC glycolysis and tumour growth." (PMID 35090076, 2022). "Analysis showed that PRMT3 regulates HIF1/VEGFA signaling pathway and tumor angiogenesis by methylating HIF1α R282 and promoting stability of HIF1α." (PMID 34753906, 2021). "IHC analysis of tumor slices before treatment showed that the expression level of PRMT3 was higher in the radiotherapy nonresponsive group." (PMID 41129671, 2026). "The differential expression analysis of the LUAD combined with LUSC datasets from the TCGA database indicates that PRMT3 exhibits higher expression in tumor tissues than in the normal tissues." (PMID 41129671, 2026).
tumor (continued). "Furthermore, our findings were corroborated by organoid cultures derived from tumor tissues of newly diagnosed patients with NSCLC, further supporting the role of PRMT3 in enhancing radiotherapy resistance." (PMID 41129671, 2026). "Analysis of tumor tissue sections from patients with NSCLC and mouse models demonstrated a significant positive correlation between PRMT3 and IDO1 expression levels." (PMID 41129671, 2026). "Additionally, the study indicates that treatment with the PRMT3 inhibitor SGC707 effectively diminishes PRMT3‐induced glycolysis and tumour growth in HCC." (PMID 39964832, 2025). "Notably, PRMT3 inhibitors such as SGC707 demonstrate preclinical promise in modulating lipid metabolism and curtailing tumor progression." (PMID 41583428, 2025). "This duality illustrates that PRMT3’s influence is not static but rather responsive to external cues within the tumor microenvironment." (PMID 41583428, 2025). "With extended DEN-CCl4 treatment, deletion of Prmt3 significantly reduced tumor burden, as evidenced by liver/body weight ratio, tumor number, and tumor size, but did not affect the incidence of tumor formation at 26-week-old." (PMID 40050608, 2025). "Here, the authors show that targeting PRMT3 markedly improves the anticancer efficacy of ICB via interrupting HSP60 methylation and oligomerization, damaging mitochondrial integrity, and thereby activating cGAS/STING-mediated anti-tumor immunity." (PMID 39256398, 2024). "Because effector CD8+ T cells secreted IFNγ and TNF to regulate anti-tumor immunity and gene expression in tumor cells, we speculated that TNF and IFNγ secreted by activated CD8+ T cells may induce PRMT3 expression in HCC." (PMID 39256398, 2024). "We treated tumor-bearing mice with anti-CD3, anti-CD4, or anti-CD8 antibodies and found that neutralization of CD3+, CD8+, or CD4+ T cells indeed attenuated the tumor growth inhibition induced by Prmt3-KO." (PMID 39256398, 2024). "Future studies are required to determine whether other PRMT3 substrates and WNT activation contribute to the functions of PRMT3 in anti-tumor immunity." (PMID 39256398, 2024). "To test this, we examined the effect of conditioned medium (CM) prepared from cultured mouse tumor-infiltrating CD8+ T cells, which were isolated from subcutaneous Hepa1-6 tumors treated with anti-PD1 therapy, on PRMT3 expression in cultured Hepa1-6 cells in vitro." (PMID 39256398, 2024). "Targeting PRMT3-dependent HSP60 methylation disrupts mitochondrial integrity and increases mitochondrial DNA (mtDNA) leakage, which results in cGAS/STING-mediated anti-tumor immunity." (PMID 39256398, 2024). "We found that HSP60-WT OE or R446K OE in the absence of PRMT3 overexpression did not promote tumor progression in Prmt3-KO Hepa1-6 cells compared to vector control, as reflected by the similar tumor volumes and tumor weights and comparable T cell infiltration." (PMID 39256398, 2024). "Altogether, these results suggest that PRMT3 is a previously unknown IFNγ-responsive gene that was up-regulated by anti-PD-1/PD-L1 therapy in HCC and may play a role in the anti-tumor immunity and the adaptive response to ICB." (PMID 39256398, 2024). "To confirm the negative correlation of PRMT3 expression with the abundance of tumor-infiltrating CD8+ T cells in the RNA-seq analyses, we performed multiplex immunofluorescence (mIF) staining of PRMT3, CD45, CD4, and CD8 on 20 cases of HCC samples." (PMID 39256398, 2024). "Notably, PRMT1, PRMT2, PRMT3, and PRMT7 exhibited upregulation, while PRMT5, PRMT6, and PRMT8 displayed downregulation in tumor." (PMID 37781030, 2023). "Furthermore, the therapeutic superiority of PRMT3 inhibition in conjunction with classical therapies was corroborated by cell‐derived xenograft (CDX) and patient‐derived xenograft (PDX) tumor model results." (PMID 37973560, 2023).
tumor (continued). "Furthermore, the administration of PRMT3 inhibitor, SGC707, disrupted the increased ADMA modification mediated by PRMT3, and abolished PRMT3‐induced HCC glycolysis and tumour growth." (PMID 35090076, 2022). "Moreover, the administration of PRMT3 inhibitor SGC707 effectively disrupted the increased ADMA modification mediated by PRMT3 and attenuated PRMT3‐induced HCC glycolysis and tumour growth." (PMID 35090076, 2022). "In the present study, we found that PRMT3 could enhance glycolysis to promote HCC growth, which provided evidence for the significance of glycolysis in tumour growth." (PMID 35090076, 2022). "Furthermore, the administration of SGC707, a selective inhibitor of PRMT3, disrupted the PRMT3‐mediated LDHA methylation and abolished PRMT3‐induced HCC glycolysis and tumour growth." (PMID 35090076, 2022). "Furthermore, a xenograft mouse model was established to investigate the effects of PRMT3 and its inhibitor, SGC707, treatment on tumour growth in vivo." (PMID 35090076, 2022). "Combination of oligomycin with heptelidic acid significantly suppressed tumor growth of PRMT3-overexpressing cancer cells but not that of parental PANC-1 cells." (PMID 31324208, 2019). "Additionally, we discuss how the action mechanisms of PRMT3 and PRMT4 in tumours could inform future cancer drug development." (PMID 39964832, 2025). "Thus, PRMT3’s role in stabilizing c-MYC creates a feedback loop that not only promotes tumor growth but also inhibits effective anti-tumor immune responses." (PMID 41583428, 2025). "To determine whether HSP60 function depends on PRMT3-mediated arginine methylation, we examined the effect of overexpressing HSP60-R446K mutant and HSP60-WT on tumor progression and T cell infiltration in the presence or absence of PRMT3 overexpression in Prmt3-KO cells." (PMID 39256398, 2024). "In addition, PRMT3 overexpression significantly promoted tumor growth in cells expressing HIF1α WT, but not in cells expressing HIF1α R282K." (PMID 34753906, 2021). "To identify the PRMT responsible for arginine methylation of NONO in CRC cells, we examined PRMT1, PRMT3, PRMT4, PRMT5, PRMT6, and PRMT8 mRNA and protein levels in paired tumor and adjacent normal tissues." (PMID 33420374, 2021).